ABCB6 (ATP binding cassette subfamily B member 6 (LAN blood group))
Description:
ATP-dependent transporter that catalyzes the transport of a broad-spectrum of porphyrins from the cytoplasm to the extracellular space through the plasma membrane or into the vesicle lumen. May also function as an ATP-dependent importer of porphyrins from the cytoplasm into the mitochondria, in turn may participate in the de novo heme biosynthesis regulation and in the coordination of heme and iron homeostasis during phenylhydrazine stress. May also play a key role in the early steps of melanogenesis producing PMEL amyloid fibrils. In vitro, it confers to cells a resistance to toxic metal such as arsenic and cadmium and against chemotherapeutics agent such as 5-fluorouracil, SN-38 and vincristin. In addition may play a role in the transition metal homeostasis (By similarity).
Synonyms: MTABC3; PRP; UMAT; EST45597; ABC; LAN
Tractability: Small molecule: a structure with a bound ligand is known; it has a binding pocket of medium quality. Antibody: UniProt places it where antibodies can reach, with high confidence; its Gene Ontology location is reachable by antibodies, with high confidence; UniProt predicts a signal peptide or a membrane-spanning region; the Human Protein Atlas places it where antibodies can reach. PROTAC: ubiquitination databases record sites on it; its protein half-life has been measured.
Target class: ATP-binding cassette; ABCB subfamily; Transporter; Primary active transporter
Gene: Protein-coding gene on chromosome 2 (219,209,766 to 219,219,012, reverse strand). Ensembl gene ENSG00000115657.
Subcellular location: Cell membrane; Mitochondrion outer membrane; Endoplasmic reticulum membrane; Golgi apparatus membrane; Endosome membrane; Lysosome membrane; Late endosome membrane; Early endosome membrane; Secreted, extracellular exosome; Mitochondrion; Endosome, multivesicular body membrane; Melanosome membrane
Subcellular location (Human Protein Atlas): Golgi apparatus; Cytosol; Mid piece; Mitochondria; Nucleoplasm; Plasma membrane; Principal piece
Pathways (Reactome):
Disease: Defective ABCB6 causes MCOPCB7
Transport of small molecules: Mitochondrial ABC transporters
Gene Ontology:
Molecular function: ABC-type heme transporter activity; ABC-type transporter activity; ATP binding; ATP hydrolysis activity; efflux transmembrane transporter activity; heme binding; tetrapyrrole binding; heme transmembrane transporter activity
Biological process: brain development; cellular detoxification of cadmium ion; heme B biosynthetic process; heme metabolic process; heme transmembrane transport; heme transport; melanosome assembly; porphyrin-containing compound biosynthetic process; porphyrin-containing compound metabolic process; skin development; tetrapyrrole metabolic process; intracellular copper ion homeostasis; intracellular iron ion homeostasis; iron ion transmembrane transport; transmembrane transport
Cellular component: endolysosome membrane; endoplasmic reticulum; endoplasmic reticulum membrane; endosome membrane; extracellular exosome; Golgi apparatus; Golgi membrane; lysosomal membrane; melanosome membrane; mitochondrial envelope; mitochondrial outer membrane; mitochondrion; multivesicular body membrane; plasma membrane; ATP-binding cassette (ABC) transporter complex; early endosome membrane; endosome; late endosome membrane; vacuolar membrane; extracellular region; membrane
Genetic constraint (gnomAD): Loss-of-function variants: 90 observed, 108.94 expected, observed/expected ratio (o/e) 0.83, 90% interval 0.7 to 0.98. The upper end of that interval is the gene's LOEUF score, 0.98, which puts it in group 4 of 6, group 1 being the genes least tolerant of losing a copy. Missense variants: 1,050 observed, 1,133 expected, observed/expected ratio (o/e) 0.93, 90% interval 0.88 to 0.98. Synonymous variants: 482 observed, 457.02 expected, observed/expected ratio (o/e) 1.05, 90% interval 0.98 to 1.14.
Gene-disease validity (ClinGen):
ClinGen rates the evidence that ABCB6 causes each of these diseases.
dyschromatosis universalis hereditaria 3 (autosomal dominant): Moderate.
microphthalmia, isolated, with coloboma 7 (autosomal dominant): Limited. Any microphthalmia, isolated, with coloboma in which the cause of the disease is a mutation in the ABCB6 gene.
Homologues: Orthologues: chimpanzee ABCB6 (99% identical), guinea pig ABCB6 (89% identical), mouse Abcb6 (89% identical), pig ABCB6 (89% identical), dog ABCB6 (88% identical), rat Abcb6 (88% identical), macaque ATG9A (80% identical), rabbit ABCB6 (77% identical), zebrafish abcb6a (63% identical), tropical clawed frog abcb6 (62% identical), zebrafish abcb6b (50% identical), Drosophila melanogaster Hmt-1 (49% identical), and 1 more. Paralogues in human: ABCB7 (33% identical), ABCB11 (23% identical), ABCB1 (23% identical), ABCB4 (23% identical), ABCB5 (22% identical), ABCB8 (21% identical), ABCB10 (21% identical), TAP2 (21% identical), ABCB9 (21% identical), TAP1 (19% identical).
Diseases named in the same sentence as ABCB6 in open-access papers:
ABCB6 is named in the same sentence as 107 diseases in open-access papers, as found by Europe PMC text mining. Sharing a sentence is not in itself a finding about the gene and the disease. The quoted sentences say what the papers report.
breast carcinoma (24 papers, 2007 to 2025). "High ABCB6 expression is related to the response to neoadjuvant chemotherapy in breast cancer and the progression of prostate cancer." (PMID 31083682, 2019). "Artesunate treatment of human CCRF-CEM leukemia and MCF7 breast cancer cells induced ABCB6 expression but repressed ABCB7 expression." (PMID 17726528, 2007). "ABCB6-mediated MDR (ATP-binding cassette sub-family B member 6) is clinically relevant in some malignancies and highly expressed in breast cancer patients with detectable minimal residual disease and in patients with hepatocellular carcinoma, as opposed to a healthy liver." (PMID 29932172, 2018).
glioma (16 papers, 2013 to 2023). A benign or malignant brain and spinal cord tumor that arises from glial cells (astrocytes, oligodendrocytes, ependymal cells). "In surgically resected glioma samples, the levels of mRNA of ABCB6 were found to be higher than the levels in normal brain tissue." (PMID 37358939, 2023). "Significant differences in mRNA expression included increases of HMBS, UROD, FECH and PPOX as well as decreases of SLC15A2, ALAD, UROS and ABCB6 in WHO IV gliomas." (PMID 32722247, 2020). "ABCB6 mRNA expression in distinctly fluorescent tumor tissues was higher than that in faintly fluorescent tumors, suggesting that ABCB6 might be responsible for PpIX accumulation in glioma cells." (PMID 35742921, 2022). "Human glioma tumors show higher ABCB6 expression than normal brain tissues." (PMID 26516850, 2015). "In this sense, we recently observed significant differences in the mRNA expression in 8 of 11 analyzed genes (HMBS, UROD, FECH, PPOX, SLC15A2, ALAD, UROS, and ABCB6) involved in the heme biosynthesis between WHO grade II and IV gliomas." (PMID 33562253, 2021). "Intriguingly, increased expressions of ABCB6, BTG1 and EPB41L4B were found in glioma, thyroid carcinoma and prostate cancer, respectively, but the underlying mechanism stays unclear." (PMID 25575809, 2015). "Moreover, we found a significant decrease of ALAD (10.33 ± 0.49 vs. 10.92 ± 0.56; p < 0.0005), UROS (9.08 ± 0.59 vs. 9.60 ± 0.51; p < 0.005) and ABCB6 (9.61 ± 0.45 vs. 9.82 ± 0.43; p = 0.019) in WHO grade IV gliomas." (PMID 32722247, 2020). "Among the altered porphyrin transporters in cancer cells, ATP-binding cassette sub-family B member 6 (ABCB6) shows higher expression in glioma tissue than in normal brain tissue and is correlated with 5-ALA/PpIX fluorescence." (PMID 28939850, 2017). "Their studies on glioblastoma cells showed higher expression of this protein in glioma cells compared with normal brain tissue, but the intracellular localization of ABCB6 does not provide unambiguous evidence regarding its influence on the degree of PpIX accumulation." (PMID 35055109, 2022). "In addition, overexpression of ABCB6, a member of the ATP-binding cassette (ABC) transporter superfamily, could enhance the accumulation of protoporphyrin IX and improve the efficacy of 5-aminolevulinic acid-based photodynamic therapy in glioma." (PMID 33954109, 2021).
hepatocellular carcinoma (9 papers, 2013 to 2025). A malignant tumor that arises from hepatocytes. "And previous studies have reported a correlation between hepatitis C virus-associated hepatocellular carcinoma and increased ABCB6 mRNA levels." (PMID 33115468, 2020). "Recent loss of function and gain of function analysis with hepatoma cell line HuH-7 revealed that ABCB6 plays a role in cell growth and proliferation by targeting the cell cycle." (PMID 23483087, 2013). "For example, a four-gene signature (ABCB6, FLVCR1, SLC48A1, and SLC7A11) was created to build diagnostic and prognostic models for hepatocellular carcinoma (HCC)." (PMID 40002678, 2025). "We identified six mRNAs (DPYSL4, HOMER1, ABCB6, CENPA, CDK1, STMN1) significantly associated with overall survival in the Cox proportional regression model for hepatocellular carcinoma." (PMID 31790363, 2019). "In the present study, we found that ABCB6 expression in hepatoma cell lines was epigenetically regulated by DNA methylation in a CpG island." (PMID 23483087, 2013). "Our results suggest that ABCB6 expression is regulated epigenetically at least partially, as ABCB6 mRNA and DNA methylation levels are inversely correlated in hepatoma cell lines." (PMID 23483087, 2013). "Overexpression of ABCB6 has been observed in hepatocellular cancer." (PMID 33066132, 2020). "Six hepatoma cell lines were used for examination of ABCB6 expressional regulation." (PMID 23483087, 2013). "ABCB6, IPO7, TIMM9, FZD7, and ACAT1, the five HBV-related genes that affect the prognosis, can work as reliable biomarkers for the diagnosis of Hepatocellular carcinoma, giving a new insight for improving the prognosis, diagnosis, and treatment outcomes of HBV-type Hepatocellular carcinoma." (PMID 36685852, 2022).
colorectal cancer (8 papers, 2016 to 2025). A primary or metastatic malignant neoplasm that affects the colon or rectum.
dyschromatosis universalis hereditaria (8 papers, 2014 to 2025). A pigmentation disease characterized by reticulate hyper- and hypo-pigmentated macules in a generalized distribution. "ABCB6 has been implicated in dyschromatosis universalis hereditaria, a condition that can present with hearing loss." (PMID 39557842, 2024). "Dyschromatosis universalis hereditaria-associated mutations in ABCB6 have been reported, but the role of this protein in the inner ear has not been studied." (PMID 39557842, 2024). "ABCB6 has been implicated in dyschromatosis universalis hereditaria, a condition characterized by hyperpigmented and hypopigmented skin macules." (PMID 39557842, 2024). "Mutations in the ABCB6 gene were implied in several hereditary diseases ranging from pseudohyperkalemia, coloboma, or dyschromatosis universalis hereditaria (DUH)." (PMID 31053883, 2019). "As a genetic disorder of abnormal pigmentation, the molecular basis of dyschromatosis universalis hereditaria (DUH) had remained unclear until recently when ABCB6 was reported as a causative gene of DUH." (PMID 24498303, 2014). "Recent studies have associated mutations in ABCB6 with various hereditary diseases including ocular coloboma, dominant familial pseudohyperkalemia and dyschromatosis universalis hereditaria (DUH)." (PMID 25360778, 2014). "Whereas Lan-negative individuals (lacking ABCB6) are healthy; mutations in the ABCB6 gene have been associated with various conditions such as ocular coloboma, dominant familial pseudohyperkalaemia and dyschromatosis universalis hereditaria." (PMID 25627919, 2015).
melanoma (7 papers, 2012 to 2025). A malignant, usually aggressive tumor composed of atypical, neoplastic melanocytes. "ABCB6 is widely expressed in tissues with high expression in heart, skeletal muscles, fetal liver, melanocytes and melanoma cells." (PMID 24224009, 2013).
pancreatic cancer (7 papers, 2014 to 2025). "However, the expression levels of ABCB6 were equivalent between PANC-1 W/T cells and clone cells by RT-PCR, and ABCB6 expression might not be related to PpIX accumulation in pancreatic cancer cells." (PMID 31083682, 2019).
lung carcinoma (6 papers, 2007 to 2025). "Therefore, the observed up-regulation in ABCB6 is likely an important initial protective response to cigarette smoke exposure that may have untoward consequences of reducing responsiveness to chemotherapeutic agents for management of lung cancers." (PMID 30655622, 2019).
porphyria (5 papers, 2016 to 2024). Porphyria is a group of diseases in which substances called porphyrins build up, negatively affecting the skin or nervous system. "Here we show that variant alleles of ABCB6 gene that are identified in individuals with severe cases of porphyrias have poor expression and/or are defective." (PMID 27507172, 2016). "Here we show that severely affected porphyria patients harbour variant alleles in the ABCB6 gene, also known as Lan, which encodes an ATP-binding cassette (ABC) transporter." (PMID 27507172, 2016). "ICU admission rate was 7.1% for porphyria patients with homozygous wild-type (WT) ABCB6 alleles versus 62.5% for those with heterozygous rare or low-frequency non-synonymous ABCB6 alleles (Fisher's exact test, P=0.0026)." (PMID 27507172, 2016). "Genetic studies on mice suggest that plasma membrane localized ABCB6 is a porphyrin exporter, and ABCB6 mutations may modify the severity of congenital porphyrias." (PMID 35832791, 2022). "Although the current porphyria cohort is small, this study indicates that among individuals with porphyrias, functionally defective ABCB6 alleles are strongly associated with disease intensification, providing new mechanistic insights into the genetics and biochemistry of porphyrias." (PMID 27507172, 2016). "On the other hand, disruption of the ABCB6 gene in mice exacerbates porphyria phenotypes in the Fech(m1Pas) mouse model, and ABCB6 is a genetic modifier of porphyria." (PMID 31053883, 2019). "Accordingly, homozygous disruption of the Abcb6 gene in mice exacerbates porphyria phenotypes in the Fechm1Pas mouse model, as evidenced by increased porphyrin accumulation, and marked liver injury." (PMID 27507172, 2016). "Because these porphyria patients are heterozygous for the variant alleles, we co-expressed each FLAG-tagged variant with V5-tagged WT ABCB6." (PMID 27507172, 2016). "Here, the authors show that a porphyrin transporter ABCB6 is a modulator of porphyria, and that patients with functionally defective ABCB6 show more severe symptoms." (PMID 27507172, 2016). "Using deep sequencing, biochemical analysis and a new mouse model, we show here that ABCB6 is a genetic modifier of porphyria that mitigates its severity by expelling porphyrins." (PMID 27507172, 2016). "Imposing Abcb6 deletion on the Fechm1Pas mouse model exacerbates porphyria symptoms, as evidenced by increased red blood cell and hepatic porphyrin concentrations, and enhanced liver injury." (PMID 27507172, 2016). "ABCB6 was revealed as a modifier of porphyria, a disease of defective heme synthesis, using whole exome sequencing of patients with well-characterized porphyria disorders, coupled with pathway analysis and a genetic porphyria mouse model." (PMID 39557842, 2024). "Thus, insufficiency of Abcb6 increases the porphyrin concentrations in tissues and excreta in a mouse model for porphyria." (PMID 27507172, 2016). "Collectively, these studies support ABCB6 role as a genetic modifier of porphyria and suggest that porphyrin-inducing drugs may produce excessive toxicities in individuals with the rare Lan(−) blood type." (PMID 27507172, 2016). "Lastly, a recent study indicates that ABCB6 mutations are not enriched in porphyria patients." (PMID 35832791, 2022). "Although elevated porphyrins are a hallmark of multiple types of porphyria, the role of porphyrin transporters (TSPO, ABCG2, ABCB6 and FLVCR1) as modulators of disease severity has not been investigated." (PMID 27507172, 2016).
coloboma (4 papers, 2014 to 2024). An abnormality in which a part of a structure in one or both eyes is missing. "It is very intriguing that the different mutations of ABCB6 can cause diverse disease phenotypes, pigmentary DUH and ocular coloboma." (PMID 24498303, 2014). "Given the involvement of ABCB6 mutations in coloboma, we performed ophthalmological examination of the DUH carriers of ABCB6 mutations and found ocular abnormalities in them." (PMID 24498303, 2014). "Our discovery has expanded the novel disease-causing mutations of ABCB6 to five, advanced our understanding of DUH pathogenesis and revealed the shared pathogenic mechanism between pigmentary DUH and ocular coloboma." (PMID 24498303, 2014).
osteosarcoma (4 papers, 2021 to 2025). A usually aggressive malignant bone-forming mesenchymal neoplasm, predominantly affecting adolescents and young adults. "We examined 198 glycolysis-related genes that showed differential expression in metastatic and non-metastatic osteosarcoma samples in the TARGET database, and identified three genes (P4HA1, ABCB6, and STC2) for the establishment of a risk signature." (PMID 33952718, 2021).
asthma (3 papers, 2019 to 2024). "In a previous study that analyzed the expression of 48 known ABC transporters in smokers with and without COPD as well as asthma diagnosis, three of them, ABCB6, ABCC1, and ABCC3, were shown to be upregulated by exposure to cigarette smoke." (PMID 38442133, 2024).
malaria (3 papers, 2018 to 2020). Malaria is a serious and sometimes fatal disease caused by a parasite that commonly infects a certain type of mosquito which feeds on humans. "Some Lan null causing mutations in ABCB6 occur at significantly higher frequencies in malaria exposed populations than in non-malaria exposed populations, but the reverse is also true for different Lan null causing mutations." (PMID 33031369, 2020). "Our analysis of ABCB6 human genomic data indicated that many coding variants are differentially enriched in populations with high versus low ancestral malaria exposure." (PMID 30271928, 2018). "Elizabeth Egan and colleagues demonstrate that host ATP binding cassette transporter ABCB6, which encodes the Langereis blood group antigen, promotes erythrocyte invasion by the malaria parasite Plasmodium falciparum." (PMID 30271928, 2018). "We identified 52 coding or splice variants in ABCB6 with a significantly different prevalence in human populations with high versus low exposure to malaria (p < 0.05)." (PMID 30271928, 2018). "Here, we assessed ABCB6 as a host factor for Plasmodium falciparum malaria parasites during erythrocyte invasion." (PMID 30271928, 2018). "A recent study assessed ABCB6 as a host factor for Plasmodium falciparum malaria parasites during erythrocyte invasion and that ABCB6 may mediate P. falciparum invasion through species protein-protein molecular interactions." (PMID 33426052, 2020).
atherosclerosis (2 papers, 2015 to 2017). A disease characterized by the build-up of fatty material and calcium deposition in the arterial wall resulting in partial or complete occlusion of the arterial lumen. "In addition, bone marrow ABCB6 deficiency was associated with accelerated atherosclerosis in mice." (PMID 28383515, 2017).
COVID-19 (2 papers, 2022 to 2024). A disease caused by infection with severe acute respiratory syndrome coronavirus 2. "As a result, it is safe to conclude that the five genes, ABCB6, KIAA1614, MND1, RIPK3, and SMG1, are truly COVID-19 specific, and the newly proposed classification method is a powerful tool." (PMID 35632517, 2022).